EPO (erythropoietin)
Diseases named in the same sentence as EPO in open-access papers (continued):
Sharing a sentence is not in itself a finding about the gene and the disease.
anemia (continued). "Although the combination of erythropoietin derivatives and intravenous iron is effective in treating anemia, the logistical burdens for those patients who are not receiving regular hemodialysis have interfered with wider adoption of these therapies." (PMID 40773297, 2025). "Pharmacological agents that enhance endogenous EPO production (e.g., HIF-PHD inhibitors) may offer dual benefits in anemia and energy metabolism disorders, though risks like erythrocytosis must be carefully managed." (PMID 41012526, 2025). "Animals lacking the Oncostatin M (OsM) receptor suffer from anemia and EPO stimulation activates OsM in erythroblasts, thereby stimulating osteoclast differentiation." (PMID 40574855, 2025). "Preoperative treatment of anemia by blood transfusion + recombinant human erythropoietin; maintenance of platelet counts at 50 × 109/L and if not necessary, embolization was not chosen." (PMID 39846269, 2025). "Nonetheless, the involvement of nephrology CNSs in balancing the anemia of dialysis patients is of great importance, regardless of the EPO adjustment, and should be acknowledged and encouraged." (PMID 40508930, 2025). "Clinically, in addition to recombinant human erythropoietin analogs, prolyl hydroxylase (PH) inhibitors to stabilize the expression of hypoxia‐inducible factor (HIF) protein were recently approved for the treatment of anemia in chronic kidney disease." (PMID 40659571, 2025). "Understanding the interplay between EPO responsiveness and RBC homeostasis may offer novel insights for optimizing anemia management in ESRD." (PMID 40643488, 2025). "This delay reduces EPO’s effectiveness at releasing iron, indicating that directly supplementing ERFE might help mobilize iron and improve anemia in CKD." (PMID 41007630, 2025). "Erythropoietin-stimulating agents are only for chemotherapy-induced anaemia with Hb < 10 g/dL, not for CRF generally." (PMID 40498265, 2025). "In ID without anemia, erythropoietin levels remain normal, but terminal erythropoiesis is altered; apoptosis decreases and late erythroblasts accumulate." (PMID 40872496, 2025). "In addition, vadadustat has been shown to increase endogenous EPO production, improve iron availability, and increase circulating reticulocytes in patients with CKD and anemia." (PMID 40790188, 2025). "Both hypoxia and anemia experiments demonstrated a robust increase in plasma EPO concentration with no detectable urinary EPO excretion in control rats." (PMID 40620843, 2025). "Although the mechanism of anemia is not well-established, ACEis have been reported to decrease plasma EPO concentration, and ARBs have been shown to inhibit angiotensin II-induced proliferation of early erythroid progenitors." (PMID 41385514, 2025). "Although anemia in this study population was not statistically significant (p > 0.05), it was found in 60% of CKD patients, which is common due to erythropoietin and iron deficiency and the dialysis procedure itself." (PMID 40143234, 2025). "Although treatment of anemia and ID with subcutaneous erythropoietin and oral iron supplementation has not been shown to be beneficial, trials of intravenous iron supplementation have shown a consistent benefit." (PMID 40718381, 2025). "Available evidence does not support the routine use of iron therapy and/or erythropoietin to treat anaemia in patients who are critically ill." (PMID 39781579, 2025). "Although not all patients with CKD stage 5 receive EPO, anemia is prevalent in this population, and studies report that 60%–85% of these patients in Taiwan are treated with EPO." (PMID 40611400, 2025). "Therapeutic nontransfusion-based anemia management options include intravenous (IV) iron and erythropoietin." (PMID 40152861, 2025). "Over time, as functional renal tissue in PKD patients further diminishes and EPO production decreases, the transplanted kidney gradually becomes the primary source of EPO, reducing the differences in anemia between PKD and non-PKD patients." (PMID 41554511, 2025).
anemia (continued). "Similarly, darbepoetin and EPO have shown comparable safety and efficacy profiles in CKD-related anemia management." (PMID 41012526, 2025). "The anemia that is common in end-stage renal disease (ESRD) patients who receive hemodialysis is typically due to a lack of erythropoietin, whose replacement raises persistent challenges in the balancing of end-stage CDK patients." (PMID 40508930, 2025). "Erythropoietin (EPO) is a glycoprotein hormone synthesized by the kidneys that is essential for stimulating red blood cell production in response to low partial pressure of oxygen (pO2), making it important in the context of anemia." (PMID 39931366, 2025). "Approved for the treatment of anemia associated with chronic kidney disease, ROX promotes endogenous erythropoietin production and improves iron homeostasis, providing a non-injectable alternative to conventional erythropoiesis-stimulating agents (ESAs)." (PMID 41020856, 2025). "This further supports the hypothesis that iron supplements can influence systemic iron metabolism and improve the anemia state by regulating HAMP and EPO." (PMID 41019553, 2025). "Antibody-mediated PRCA subjects were characterized as having little or no circulating erythropoietin, a bone marrow biopsy devoid of red blood cell precursors, severe anemia, and the presence of antibodies capable of binding to and neutralizing erythropoietin." (PMID 39737166, 2024). "The erythropoietin-damaged bone marrow would no longer be able to manufacture new erythrocytes following their breakdown in the spleen, and anemia symptoms would manifest." (PMID 38989377, 2024). "In our study, we demonstrated that hepcidin levels were significantly higher in IPF patients compared to the control group, independent of anemia, EPO, and systemic inflammation." (PMID 39597967, 2024). "Since erythropoietin is primarily produced by renal cortical peritubular cells, effects of SGLT‐2 inhibition on anaemia could represent an example of systemic effects mediated by proximal tubule SGLT‐2 inhibition, independent of circulating glucose levels." (PMID 39267208, 2024). "Owing to concern for hemolytic anemia/TMA, a full workup of anemia was done which revealed a negative direct and indirect Coombs test, elevated erythropoietin, and iron panel consistent with anemia of chronic disease." (PMID 39722000, 2024). "In anemias with ineffective erythropoiesis (like thalassemia and SCD), most erythroblasts do not effectively differentiate into mature erythrocytes, leading to anemia and boosted EPO production by the kidneys." (PMID 39337010, 2024). "The administration of erythropoietin has not been shown to decrease postburn anemia or the requirements for blood transfusion." (PMID 39202529, 2024). "The Baltimore Longitudinal Study on Aging reported that EPO levels increased with age in healthy individuals without anemia, particularly in those without diabetes or hypertension." (PMID 38610814, 2024). "A study reported that despite patients suffering from severe anemia, erythropoietin levels did not increase in case of chronic intoxication with Cd." (PMID 38784687, 2024). "Studies on animal models with experimentally induced anaemia have indicated that suppression of hepcidin expression is dependent on erythropoiesis and not directly mediated by hypoxia, anaemia, or EPO." (PMID 38892911, 2024). "Using high-dose EPO for the complete correction of anemia or to achieve a high hemoglobin level, no reduction in the risk of cardiovascular events was observed; rather, there was an increased risk of serious cardiovascular events and mortality." (PMID 38628440, 2024). "Studies were included if they discussed IDA, GI neoplasms, use of iron supplementation (with or without erythropoietin-stimulating agents [ESAs]), defined anemia and had an adult patient population." (PMID 38776289, 2024).
anemia (continued). "EPO-agonist, although widely used for transfusion-dependent anemia, appeared to be not enough to achieve red cell engraftment in patients with erythroid precursor aplasia." (PMID 39015495, 2024). "Further, 82 studies were excluded, because iron with or without erythropoietin was supplemented in non-surgical anemic patients, or as prevention of anemia expected to develop after surgery." (PMID 38167004, 2024). "Hypoxia-inducible factor prolyl hydroxylase (HIF-PH) inhibitors are a new class of anti-anemia agents that inhibit PH activity to stabilize HIF-α and promote the production of endogenous EPO, thereby enhancing the production of hemoglobin (Hb) and erythrocytes." (PMID 38429779, 2024). "However, anaemia is a common complication of CKD, since with CKD, the kidneys are damaged and thus EPO production decreases." (PMID 39682316, 2024). "Clinical trials with these compounds demonstrated that they are at least as effective as recombinant EPO in treating or correcting anemia in non-dialysis and dialysis patients." (PMID 38672425, 2024). "Haemoglobin levels can be supported with erythropoietin therapy, temporary dose reduction or red cell transfusions, and anaemia in the first few months does not necessarily require a change of JAKi therapy." (PMID 39604140, 2024). "Notably, this benefit on anemia was consistently observed in moderate-to-severe CKD, where kidney erythropoietin production is impaired." (PMID 38913113, 2024). "Half of the patients in the cohort were also treated with erythropoietin, although this treatment was not used in eight patients who had severe anemia." (PMID 39274330, 2024). "Indeed, in recent years, expanding treatment options in MDS have included some important novel therapies for anaemia in RS-MDS, like luspatercept, which has proven to be more effective than EPO in LR-MDS patients and those affected by SF3B1-mutant MDS." (PMID 38672645, 2024). "For example, a case series of 5 pregnant women with CKD demonstrated an absence of EPO response to anemia." (PMID 38707831, 2024). "We had to exclude twenty RCTs that investigated iron and/or erythropoietin supplementation in anemia but did not further diagnose the reason for anemia before enrolment of all study participants." (PMID 38167004, 2024). "Experimental studies revealed that after life-supporting pig-to-NHP renal xenotransplantation, long-term surviving recipients not supplemented with human EPO gradually developed anemia." (PMID 38517040, 2024). "Treatment of anemia with erythropoietin in HF has no impact on the overall prognosis, and darbepoietin has even been associated with an increased rate of thromboembolism." (PMID 38137939, 2023). "The recommendations in case of anemia in this population consist of erythropoietin and iron supplementation rather than transfusion." (PMID 37038581, 2023). "Jeffery and his colleagues defined an anaemic event as the drop of Hb to less than 10 g/dl, the use of blood transfusion or EPO therapy, whereas CIA in our study was defined as patients who develop anaemia from normal Hb or had worsening severity of anaemia post-chemotherapy." (PMID 37223288, 2023). "Age, serum erythropoietin levels and anti-erythropoietin antibodies levels among the P. falciparum-infected pregnant women stratified by the presence or absence of anaemia." (PMID 36989322, 2023). "Third, due to the retrospective nature of the study, we excluded 182 out of the total 286 patients with anemia without a clear etiology due to a lack of EPO data." (PMID 37741889, 2023). "Erythropoietin (EPO), an important indicator and trigger of EMH, is commonly used to treat anemia." (PMID 37415162, 2023). "Possible explanations are either that the associations of anemia with CKD and HF prognosis do not reflect direct causality but residual confounding or reverse causality, or the use of EPO/ESA increases risk through other side effects outside of erythropoiesis." (PMID 37763045, 2023).
anemia (continued). "Anaemia was treated with oral iron supplementation, and no trial participants received erythropoietin or immunosuppresants for glomerulopathies or other indications during the course of the trial." (PMID 36442482, 2023). "Finally, it is beyond the scope of this study to explore the mechanisms between anemia and serum Klotho, and we lack data on FGF23 and EPO to further explore the mechanisms involved." (PMID 36797683, 2023). "Therefore, in this study, we aim to shed a light on erythropoietin serum levels in patients with chronic obstructive pulmonary disease (COPD) and anemia, along with a review of previously reported studies." (PMID 37117600, 2023). "An increase in EPO levels was observed in infected Cish+/+ but not Cish−/− mice, most likely because severe anemia was observed only in Cish+/+ mice." (PMID 38029163, 2023). "The early initiation of erythropoietin in pre-dialysis patients with non-severe anemia significantly slows the progression of renal disease and delays the initiation of renal replacement therapy." (PMID 37754834, 2023). "Non-regenerative anemia usually presents in the advanced stage of chronic kidney disease (CKD), which is associated with inadequate production of erythropoietin (EPO) due to the loss of functional renal parenchyma." (PMID 36855344, 2023). "On the other hand, the long-term anemia group had higher creatinine, urea, serum IL-6, sFas levels, EPO/Hb, and sFas/eGFR ratio at baseline than the patients without long-term non-anemia." (PMID 37390095, 2023). "Fourth, we did not measure erythropoietin, B12, and folate levels in our participants, so the lack of definition of anemia etiology was another limitation." (PMID 36894956, 2023). "Low hemoglobin levels, however, should be interpreted with caution in order not to mistake dilution-related pseudo-anemia for true anemia, especially if under erythropoietin treatment." (PMID 38202020, 2023). "Significant differences were observed in cases of advanced age, smoking, hypertension, obesity, seniority of dialysis, anemia, and absence of treatment by erythropoietin." (PMID 38282781, 2023). "We now recommend using EPO at a baseline Hb level of 11 g/dl in ACD patients without nutritional anemia." (PMID 38041115, 2023). "Regardless of the possible significant influence of anti-EPO antibodies in the development of anaemia, no known study, to the best of our knowledge, has assessed anti-erythropoietin antibodies in pregnancy." (PMID 36989322, 2023). "The common causes of anemia in CKD patients include insufficient production and decreased activity of erythropoietin (EPO), lack of hematopoietic raw materials, hyperparathyroidism, shortened lifespan of red blood cells, and inflammation." (PMID 36799117, 2023). "However, the blunted erythropoiesis, decreased EPO production, shortened RBC survival, and dysregulation in iron homeostasis eventually result in anemia of chronic disease." (PMID 37065412, 2023). "Physicians may have been influenced by the severity of anemia or suspicion of MDS, which could have affected their decision to test EPO levels in the patients." (PMID 37741889, 2023). "Of note, even with a slight difference, EPO levels were also significantly increased when compared to those of CDAII patients, probably due to a greater hemolytic component and the higher degree of anemia in PKD than CDAII." (PMID 36927785, 2023). "We believe that EPO therapy is indicated prior to the TK procedure in ACD patients without nutritional anemia who have a preoperative baseline Hb < 11 g/dl." (PMID 38041115, 2023). "EPO production from the liver also occurs under moderate to severe hypoxic conditions but is not enough to improve anemia under renal dysfunction or inflammatory conditions." (PMID 36769359, 2023). "Treatment with erythropoietin is well established for anemia in chronic kidney disease patients but not well studied in acute kidney injury." (PMID 35279078, 2022).
anemia (continued). "Anemic lepromatous leprosy patients have shown to have a blunted erythropoietin response compared with controls having non-inflammatory anemia." (PMID 35449687, 2022). "Therefore, recombinant human EPO (rHuEPO) and other erythropoiesis-stimulating agents (ESAs) are used for the treatment of MDS-related anemia." (PMID 35821550, 2022). "ESAs induce anemia response rates of 40–45%, and favorable responses have been associated with milder anemia (absence of RBC transfusion dependence), and lower erythropoietin levels at baseline." (PMID 35045875, 2022). "Anemia frequency increases as CKD progresses, as is well-known, but the percentage of patients with hemoglobin above 10.6 g/dl (in CKD stages IV-V) slightly increased in the Nephrocare group, and 17.9% received erythropoietin." (PMID 36240220, 2022). "These animals also develop anemia although serum erythropoietin, which is produced in the kidney, was not altered." (PMID 35832553, 2022). "Animal models of anemia including the streptozotocin (STZ)-induced spontaneously hypertensive rats (SHR) and the cisplatin (CDDP)-induced C57BL/6J mice are established to study the TBN’s effects on expression of hypoxia-inducible factor and erythropoietin." (PMID 36324690, 2022). "We selected randomized controlled trials comparing daprodustat with recombinant human erythropoietin (rhEPO) in anemia patients with CKD with or without dialysis." (PMID 35359863, 2022). "Negative iron balance is a critical contributor to anemia in CKD patients apart from inflammation and erythropoietin (EPO) deficiency." (PMID 35690731, 2022). "Anemia was present in 6 out of 7 patients and there was a trend towards a negative correlation between endogenous EPO levels and hemoglobin (Hb; r = -0.5357, P = 0.2357) or hematocrit (r = -0.6071, P = 0.1667) at hospital admission." (PMID 36211426, 2022). "Recombinant human erythropoietin (rhEPO) or its analogs (erythropoiesis-stimulating agents [ESAs]) and iron supplementation (intravenous and/or oral) represent the current standard of treatments for CKD patients with anemia (Drüeke and Parfrey, 2012)." (PMID 35359863, 2022). "It is worth noting that in AT, the induction of anemia is independent of the concentration of erythropoietin (EPO)." (PMID 36420267, 2022). "In renal disease, the hypoxic induction of EPO fails and anemia becomes more severe as the disease progresses without concomitant rise in EPO production." (PMID 35445830, 2022). "Previous studies have shown that prophylactic erythropoietin reduces the negative consequences of chemotherapy-induced severe anemia and improves the patients’ health-related quality of life." (PMID 36267984, 2022). "In gnotobiotic piglets with EHEC infection and in mice after Stx challenge, we found an increase in EPO expression despite an absence of anemia in these animal models." (PMID 36211426, 2022). "The level of blood immunoreactive erythropoietin in HIV patients did not rise in lockstep with progressive anemia." (PMID 36676716, 2022). "In patients with chronic HF and anemia, extraneous erythropoietin did increase the hemoglobin concentration but failed to improve the prognosis of HF." (PMID 35600475, 2022). "Despite the absence of anemia in Stx+vehicle mice, EPO plasma levels were elevated compared with sham mice." (PMID 36211426, 2022). "In conclusion, this pragmatic trial showed that erythropoietin treatment had no impact on transfusions' need, renal recovery or mortality in acute kidney injury patients with anemia." (PMID 35279078, 2022). "Thus, anemia of CKD was treated mainly by recombinant human erythropoietin (rhEPO), EPO stimulating agents (ESAs), and iron supplements." (PMID 35628849, 2022). "We found that endogenous EPO was elevated in plasma of humans, piglets, and mice with HUS, regardless of species and degree of anemia, suggesting that EPO signaling plays a role in HUS pathology." (PMID 36211426, 2022).